WDR24 (WD repeat domain 24)
Description:
Catalytic component of the GATOR2 complex, a multiprotein complex that acts as an activator of the amino acid-sensing branch of the mTORC1 signaling pathway. The GATOR2 complex indirectly activates mTORC1 through the inhibition of the GATOR1 subcomplex. GATOR2 probably acts as an E3 ubiquitin-protein ligase toward GATOR1. In the presence of abundant amino acids, the GATOR2 complex mediates ubiquitination of the NPRL2 core component of the GATOR1 complex, leading to GATOR1 inactivation. In the absence of amino acids, GATOR2 is inhibited, activating the GATOR1 complex. In addition to its role in regulation of the mTORC1 complex, promotes the acidification of lysosomes and facilitates autophagic flux. Within the GATOR2 complex, WDR24 constitutes the catalytic subunit that mediates 'Lys-6'-linked ubiquitination of NPRL2.
Synonyms: C16orf21; JFP7; DKFZp434F054
Tractability: PROTAC: UniProt records ubiquitination sites on it; ubiquitination databases record sites on it; its protein half-life has been measured.
Gene: Protein-coding gene on chromosome 16 (684,621 to 690,444, reverse strand). Ensembl gene ENSG00000127580.
Subcellular location: Lysosome membrane
Subcellular location (Human Protein Atlas): Vesicles; Cytosol
Pathways (Reactome):
Cellular responses to stimuli: Amino acids regulate mTORC1
Gene Ontology:
Molecular function: protein binding; ubiquitin protein ligase activity
Biological process: cellular response to amino acid starvation; cellular response to nutrient levels; positive regulation of TOR signaling; positive regulation of TORC1 signaling; protein K6-linked ubiquitination; protein localization to plasma membrane; regulation of autophagy; negative regulation of TORC1 signaling; positive regulation of macroautophagy; protein ubiquitination
Cellular component: GATOR2 complex; lysosomal membrane; vacuolar membrane
Genetic constraint (gnomAD): Loss-of-function variants: 32 observed, 59.78 expected, observed/expected ratio (o/e) 0.54, 90% interval 0.4 to 0.72. The synonymous counts are far from expectation, so gnomAD's model fits this gene poorly and the ratio says little. Missense variants: 977 observed, 1,117.9 expected, observed/expected ratio (o/e) 0.87, 90% interval 0.83 to 0.92. Synonymous variants: 565 observed, 461.87 expected, observed/expected ratio (o/e) 1.22, 90% interval 1.14 to 1.31.
Homologues: Orthologues: chimpanzee WDR24 (100% identical), macaque WDR24 (99% identical), rat Wdr24 (96% identical), guinea pig WDR24 (96% identical), pig WDR24 (96% identical), mouse Wdr24 (96% identical), dog WDR24 (95% identical), tropical clawed frog wdr24 (79% identical), zebrafish wdr24 (71% identical), Drosophila melanogaster Wdr24 (38% identical). Paralogues in human: GEMIN5 (18% identical), WDR59 (16% identical), WDR77 (8% identical), PEX7 (8% identical), RBBP4 (8% identical), GRWD1 (7% identical), RBBP7 (7% identical), WDR73 (6% identical), ERCC8 (6% identical).
Diseases named in the same sentence as WDR24 in open-access papers:
WDR24 is named in the same sentence as 4 diseases in open-access papers, as found by Europe PMC text mining. Sharing a sentence is not in itself a finding about the gene and the disease. The quoted sentences say what the papers report.
liver cancer (1 paper, 2023). An epithelial or non-epithelial malignant neoplasm that arises from the liver. "To confirm this hypothesis, we conducted WDR24, a component of GATOR2, and TET2 single/double KO in liver cancer cells and examined their effects on mTORC1 activity and tumor growth using xenograft model." (PMID 37550284, 2023).
cancer (1 paper, 2022). A tumor composed of atypical neoplastic, often pleomorphic cells that invade other tissues. "The top 100 JMJD8 coexpressed genes in pan-cancer were analyzed on GEPIA2.0, and the top 5 genes (C16ORF58, IFT140, ITFG3, PIGQ, and WDR24) showed high correlations with JMJD8 in the majority of cancer types." (PMID 35898493, 2022).
tumor (1 paper, 2023). "WDR24 KO abolishes mTORC1 activation and tumor growth advantage induced by TET2 deficiency." (PMID 37550284, 2023).
WDR24 also shares sentences with these, for which no sentence is quoted: cardiac hypertrophy (1 paper).